S100A7 (S100 calcium binding protein A7)
Diseases named in the same sentence as S100A7 in open-access papers (continued):
Sharing a sentence is not in itself a finding about the gene and the disease.
psoriasis (continued). "In addition, by confirming that AOA significantly reduced the expression of psoriasis-associated antimicrobial peptides (Defb4, Lcn2, S100a7, and S100a9), we revealed that AOA ameliorated psoriasis-related symptoms and had anti-inflammatory effects in a mouse model of psoriasis." (PMID 37649889, 2023). "Our results showed that administration of gentamicin alleviated pathogenesis of psoriasis-like symptoms, including alleviating psoriasiform skin inflammation, a decrease in the skin epidermis thickness, decreasing mRNA expression of IL-17A, IL-23, S100A7, and increased mRNA expression of KRT10." (PMID 36710269, 2023). "However, there is extensive information in the literature about the role of S100A7 in psoriasis." (PMID 35892571, 2022). "However, the evidence of S100A7 involvement in the pathogenesis of psoriasis is growing." (PMID 32377165, 2020). "Thus, targeting S100A7-/S100A15-mediated inflammatory loop may have beneficial effect in the treatment of psoriasis, as shown for the vitamin D analoque calcipotriol and TNF-α inhibitors." (PMID 24901012, 2014). "Interestingly, stimulation of keratinocytes with a combination of IL-17A, IL-22 and TNFα increased S100A7 production, which may form a feed-back loop, amplifying inflammation in psoriasis and other conditions." (PMID 23285311, 2012). "Molecules such as S100A7 (psoriasin) and squamous cell carcinoma antigen 2 (SCCA2), which are induced by IL-17/IL-22 in psoriasis, are also overexpressed in oral SCC and have been shown to promote keratinocyte proliferation and invasion." (PMID 41009535, 2025). "SPRR2C expression was significantly upregulated in psoriasis skin samples and in vitro cellular lines in response to IL-22 stimulation through the miR-330/STAT1/S100A7 axis." (PMID 40725772, 2025). "The downregulated genes detected at day 14 in these populations included inflammatory molecules (e.g., IL36G, S100A7/A8/A9) and structural proteins (GJB2, KRT16/17), known to be over-expressed in the upper layers of the psoriasis epidermis." (PMID 38291032, 2024). "Following the decrease in Livin expression, a substantial reduction was observed in the levels of inflammatory mediators, namely, MMP‐7, Cath B, CXCL 6, S100A8, S100A7, and S100A11, which have crucial functions in psoriasis." (PMID 38332513, 2024). "Hence, AMPs such as LL-37 and S100A7 could present novel targets for treating these diseases characterized by skin barrier disorders in cases where it is challenging to distinguish between AD and psoriasis or when these conditions overlap." (PMID 38606161, 2024). "We found GPR15LG knockdown down-regulated the expressions of IL-1α, TNF-α, IL-1β and S100A7 in M5-treated HaCaT cells, suggesting a pivotal role of GPR15LG in keratinocyte-mediated inflammation in psoriasis." (PMID 38393364, 2024). "The expression levels of several S100 proteins, such as S100A2, S100A7, S100A8/S100A9, S100A12, and S100A15, are significantly up-regulated in psoriasis-involved skin." (PMID 37346040, 2023). "S100A7, S100A8, and S100A9 were markedly over-expressed in all three layers in PP, consistent with previous psoriasis studies." (PMID 37308489, 2023). "S100A7, an AMP with a strong antimicrobial activity, which is first identified in the epithelial cells of human psoriasis skin, has been proved to play a critical role in IRR against the invasion and infection of pathogenic microorganisms." (PMID 36428305, 2022). "Typically, during the immunopathogenesis of psoriasis, injured epidermal keratinocytes can release LL37 and S100A7, which activate DCs and initiate subsequent immune cell recruitment and interleukin (IL)‐23/Th17 cell axis inflammatory cascades." (PMID 35716036, 2022). "In support of the preceding finding, new research has revealed significantly elevated expression of alarmins, such as IL-33, HMGB1, S100A7, and S100A12, in serum, implying a role for these alarmins in the immunopathology of psoriasis conditions." (PMID 35892571, 2022).
psoriasis (continued). "To further validate the correlation of STAT1 and S100A7 with SPRR2C in psoriasis, we next evaluated the STAT1 and S100A7 protein levels and distribution in the psoriatic lesional and normal control tissue samples." (PMID 33452236, 2021). "In contrast, the anti-bacterial peptide S100A7 and the chemokine CCL20 that are frequently used as markers of psoriasis were moderately changed in the model group." (PMID 33986690, 2021). "After injection of LCN2 into imiquimod (IMQ)-induced psoriasis-like skin, the mRNA expression levels of IL17A, CXCL1, CCL20, S100A7, and other cytokines and chemokines increased, which supports our analysis results." (PMID 33613635, 2021). "IκBζ is an important regulator of several psoriasis-related genes, including IL-17A downstream genes such as DEFB4, S100A7, and IL-6." (PMID 34445513, 2021). "S100A7 and HBD-2, known as antimicrobial peptides, are related to innate and adaptive immunity, and IL-6 affects keratinocyte proliferation in psoriasis." (PMID 34445513, 2021). "S100A7 is induced by calcium, vitamin D, retinoic acid, bacterial products, TNF-α, IL-17A and IL-22, and is involved in the pathogenesis of psoriasis via its chemotactic activity for neutrophils and CD4+ T lymphocytes." (PMID 32947991, 2020). "S100A7 (psoriasin), S100A8 (calgranulin A), S100A9 (calgranulin B), S100A12 (calgranulin C), and S100A15 are highly expressed in psoriasis." (PMID 33050592, 2020). "The proteins identified by LC–MS/MS, including SFN, GSTP1, FABP5, S100A7, and RABP2, were also observed to be upregulated in psoriasis lesional tissues." (PMID 32817748, 2020). "Results from qRT-PCR measurements of psoriasis-relevant transcripts showed that levels of DEFB4B, IL36G, LCN2, S100A7, S100A8 mRNA were significantly decreased in rhodomyrtone-treated cultures when compared with cytokine-treated cultures (p<0.0001, all)." (PMID 30321197, 2018). "S100A7 (psoriasin), S100A8 (calgranulin A), S100A9 (calgranulin B), and S100A12 (calgranulin C) are markedly increased in psoriasis lesions." (PMID 29619128, 2018). "S100A7 and S100A7A are constitutively expressed in the skin and can be present at high levels during disease or inflammation, such as, for example, psoriasis." (PMID 27355424, 2016). "S100A7 and S100A15 are upregulated in psoriasis by similar mediators and synergize to promote inflammation." (PMID 24901012, 2014). "Our findings indicate that S100A7, SERPINB13, and PLBD1 may contribute to the inflammatory process of psoriasis by impacting macrophages infiltration, especially in LS samples." (PMID 38699235, 2024). "By downregulating S100A7 expression, this may decrease the production of TNF, IL-6, and IL-8 from neutrophils, which are known to play a crucial role in the pathogenesis of psoriasis." (PMID 38699235, 2024). "To further investigate whether Gpr15lg can regulate immune response in psoriasis, we detected the level of IL-1α, TNF-α, IL-1β and S100A7 by qRT-PCR and IHC." (PMID 38393364, 2024). "One study points out that upregulation of S100A7 is not restricted only to psoriasis; strong S100A7 expression was also found in atopic dermatitis, mycosis fungoides, Darier’s disease, and lichen sclerosus et atrophicus." (PMID 38892279, 2024). "Additionally, serum S100A7 (psoriasin) and S100A12 (calgranulin-c) were found to be elevated in psoriasis patients, with the latter being regarded as the most promising S100 protein biomarker thus far in terms of correlating with severity of psoriasis." (PMID 37546687, 2023). "The severity of psoriatic inflammation indicated by the Psoriasis Area and Severity Index (PASI) was positively correlated with S100A7 expression in the epidermis, which was downregulated during biological treatment with adalimumab, etanercept, ustekinumab, or a neutralizing antibody against IL-17A." (PMID 37891988, 2023).
psoriasis (continued). "The S100A7/E-FABP complex is also involved in lipid transport and metabolism during epidermal barrier formation, and modulation of cell differentiation and migration in some dermatoses such as psoriasis." (PMID 37346040, 2023). "Small subsets of S100 (for example, S100A7, S100A8, S100A9, and S100A12) have been shown to be upregulated in psoriasis skin lesions, whereas transcriptomics and ELISA-based approaches indicate that S100A12 is strongly correlated with a functional disease condition." (PMID 35892571, 2022). "Members of the S100 family of proteins intensively studied in the course of psoriasis include S100A4 (Figure A1), S100A7 (Figure A2), S100A8 (Figure A3), S100A9 (Figure A4), S100A12 (Figure A5), S100B (Figure A6) and S100A15, indicating their involvement in the pathogenesis of the disease." (PMID 36235175, 2022). "HMGB1, IL-33, S100A7, and S100A12 were chosen as the most promising alarmins according to the literature, because they were reported to be elevated in various autoimmune diseases, yet their role in pathophysiology of psoriasis is still unclear." (PMID 32377165, 2020). "Some studies have shown decreased levels of IL-17A, TNF-α, S100A15, S100A7, S100A9 and IL-6 gene expression in PBMCs after NB-UVB treatment in patients with psoriasis whereas other pro-inflammatory mediators such as sVCAM-1, sICAM-1, sE-selectin, MMP-9, and MPO showed no significant reduction." (PMID 30865695, 2019). "For example, S100A4 is involved in autoimmune pancreatitis, S100A11, S100A8 and S100A9 in rheumatoid arthritis, S100A1 in hypoxia-induced inflammatory response in cardiomyocytes, S100A12 in Crohn’s disease, S100A7 and S100A7A in psoriasis, S100A8, S100A9 and S100A12 in systemic lupus erythematosus." (PMID 30018736, 2018). "The list of the DEG in common in the 4 studies contains many genes known to be upregulated in psoriasis, such as IFNγ-regulated genes STAT-1, STAT-3 and MX1; antimicrobial peptides (beta defensin 4, lipocalin 2, S100A7); and pro-inflammatory proteins such as IL-8, CXCL1, IL-1F9, TNFSF10/TRAIL." (PMID 20422035, 2010). "Although S100A7 is constitutively expressed at relatively low levels in normal keratinocytes, its expression levels are dramatically increased in psoriatic lesions, suggesting its key role in response to inflammatory stimuli and the pathogenesis of psoriasis." (PMID 37346040, 2023). "Interaction of S100A7 with RAGE activates p38 MAPK (mitogen-activated protein kinase) and ERK (extracellular signal-regulated kinase) signaling pathways, leading to production of multiple inflammatory mediators involved in psoriasis, including IL-1α, IL-1β, IL-6, IL-8, TNF-α." (PMID 37346040, 2023). "However, overexpression of S100A7 led to aberrant keratinocyte differentiation in psoriasis, suggesting a negative feedback during psoriasis development." (PMID 35075118, 2022). "The alarmins HMGB1, IL-33, S100A7, and S100A12 were significantly elevated in the serum of patients, which states the hypothesis that they play specific roles in the immunopathology of psoriasis." (PMID 32377165, 2020). "Twenty-one S100 proteins are known, of which S100A7 (psoriasin), S100A8 (calgranulin A), S100A9 (calgranulin B), S100A12 (calgranulin C), and S100A15 have antimicrobial effects and their expression levels are increased in the lesional skin and serum of psoriasis patients." (PMID 32947991, 2020). "Furthermore, IL-1β stimulation of NHEKs was found to induce upregulation of the mRNA and protein levels of pro-inflammatory cytokines, chemokines and antibiotic peptides including IL-36γ, CXCL1, CXCL2, CCL20, S100A7, S100A8 and S100A9, which are closely related to the pathogenesis of psoriasis." (PMID 32194991, 2020). "Therefore, the authors concluded that S100A7 is not a promising serum biomarker for psoriasis." (PMID 29619128, 2018).
psoriasis (continued). "Recapitulating psoriasis skin, IL-17A+TNF-α treatment lead to increased expression of DEFB4, PI3, LCN2, S100A7, and IL36G mRNA over a 72 h time course without marked deterioration of tissue structure." (PMID 30321197, 2018). "Most well known psoriasis related genes activated in non-lesional skin are IL6, IL22, IL36A, IL36G, IL19, IL20, S100A7 and S100A12." (PMID 25897967, 2015).
breast carcinoma (56 papers, 2005 to 2025). "In breast cancer, S100A7 was associated with immunomodulators, the major histocompatibility complex, chemokines, and receptors." (PMID 38499391, 2024). "High S100A7 expression was associated with the invasiveness, migration, proliferation and chemotherapy resistance of breast cancer cells in vitro experiments." (PMID 38499391, 2024). "The Transwell assay demonstrated that S100A7 was associated with the invasion and migration of breast cancer cells." (PMID 38499391, 2024). "Further, S100A7 was related to tumor mutational burden, tumor heterogeneity, methylation and tumor stemness in breast cancer." (PMID 38499391, 2024). "KM plotter analysis also revealed high expression of S100A7 with enriched macrophage populations significantly associated with the poor recurrence-free survival (RFS) of breast cancer patients." (PMID 35135586, 2022). "This study calls for oncologist’s attention to the previously neglected breast cancer commensal microbiota and highlights the role of bacterial components and its associated LPS/S100A7/TLR4 signaling cascade in the breast tumor microenvironment." (PMID 33969603, 2022). "We further demonstrated that cPLA2 inhibition caused reduced production of PGE2 only in S100A7 expressing breast cancer cells." (PMID 35135586, 2022). "Overall, increased level of LPS in the mammary tumor was found to be positively associated with S100A7 and inversely correlated with TLR4 expression." (PMID 33969603, 2022). "Our data are in line with recently published studies indicating that S100A7 immunoreactivity is associated with worse prognostic factors, including distant metastasis-free interval and breast cancer-specific survival in ER-positive stage I-III BCs." (PMID 33557316, 2021). "Here, the high mRNA expression of S100A7 was associated with worse OS in grade II breast cancer, and modestly associated with poor survival for all breast cancer patients (p = 0.059)." (PMID 28051137, 2017). "Further studies are required to explore the potential application of anti-inflammatory drugs for obese patients to reduce the risk of breast cancer progression for S100A7+ patients." (PMID 28629450, 2017). "Kaplan-Meier analysis also demonstrated that the S100A7+ group was significantly associated with poor clinical outcome in terms of both breast cancer-specific survival (P = 0.0101) and relapse-free survival (RFS) (P < 0.0001)." (PMID 28629450, 2017). "The clinical relevance of this was supported by patient data of the TCGA cohort, which showed that S100A7 upregulation is more likely to be associated with increased miR-29b expression in ER+ breast cancer patients than ER− patients and vice versa." (PMID 25622979, 2015). "A number of epithelium-associated malignancies have increased expression of S100A7: carcinoma of the breast, lung, prostate, stomach and cutaneous squamous cell carcinoma." (PMID 23285311, 2012). "We observed that S100A7 expression was associated with increased blood vessel density in mouse models of human breast cancer." (PMID 18320059, 2008). "SBEM protein, however, was more frequently expressed in ER− breast cancers, consistent with its positive association with psoriasin/S100A7 and HER-2." (PMID 18269587, 2008). "This was of interest since ERα has been reported to have variable expression in chemical carcinogen induced tumors and we have previously shown an inverse association of human psoriasin/S100A7 expression with ERα in breast cancer." (PMID 15717926, 2005). "Since S100A7 was closely associated with all these factors, we hypothesized that it might be involved in the development of chemotherapy resistance in breast cancer." (PMID 38499391, 2024). "Accumulated evidence shows that S100A7 overexpression is associated with breast cancer malignancy." (PMID 28629450, 2017). "S100A7 overexpression was also associated with increased malignancy of breast cancer, which may occur through stimulation of Jab1 activity." (PMID 18793447, 2008).